FAP (fibroblast activation protein alpha)
Diseases named in the same sentence as FAP in open-access papers (continued):
Sharing a sentence is not in itself a finding about the gene and the disease.
tumor (continued). "Third, FAP-CAR T cells reprogrammed the immunosuppressive milieu such that they retained their functionality and also prevented loss of function of subsequently administered Meso-CAR T cells and tumor-infiltrating endogenous T cells when given in combination with anti-PD1." (PMID 37607999, 2023). "Our study provides new insights into FAP from a pan-cancer perspective, indicates that FAP may serve as a prognostic biomarker and promising therapeutic target in tumor treatment, and offers new clues for developing novel targeted anti-tumor treatment." (PMID 37166418, 2023). "Interestingly, opposite effects on immune cell composition were observed when the distinct CAF populations were eliminated, with enhanced anti-tumour immunity and an immunosuppressive environment developing when FAP+ or αSMA+ fibroblasts were targeted, respectively." (PMID 36480035, 2023). "FAP has been shown to be highly expressed by cancer-associated fibroblasts (CAFs) in multiple epithelial cancers with generally absent FAP expression in the tumor cells." (PMID 37333052, 2023). "However, studies of a pancreatic ductal adenocarcinoma (PDAC) mouse model have also identified tumor-restraining α-SMA+ CAFs (rCAFs) and tumor-promoting FAP+ CAFs (pCAFs), which are involved in the aggregation of regulatory T cells, suggesting the complexity of α-SMA+ CAF function." (PMID 37143134, 2023). "Moreover, FAP-targeted radioligand therapy could be more effective if further improvements in tumor retention and absolute uptake are achieved." (PMID 37321827, 2023). "Since some of the previous studies reported that FAP may promote tumor progression by altering the intra-tumoral immune milieu and helping tumor cells escape immune surveillance, here we investigated the correlation between FAP expression and immunosuppressive signatures using the TISIDB database." (PMID 37166418, 2023). "Moreover, we found FAP-CAR T cells enhanced the anti-tumor activity of anti-PD-1 suggesting that FAP-CAR T cells alone may have an inherent capacity to modulate the endogenous immune landscape." (PMID 37607999, 2023). "Furthermore, FAP-positive CAFs upregulate the expression of immunosuppressive genes of MDSCs, making their ability to inhibit T-cell proliferation more effective and antagonizing anti-tumor interferon-gamma (IFNγ)+T-cell immunity." (PMID 38313431, 2023). "This suggests that FAP overexpression could be a method to enhance tumor infiltration by NK cells." (PMID 38196606, 2023). "Hence, FAP radioligands are considered important tools for in vivo tumor imaging and/or therapy." (PMID 37284857, 2023). "FAP+CAFs have also been associated with the recruitment of regulatory FOXP3+-T lymphocytes, and in agreement with this, we find that the decrease in regulatory T cells we observe in the TME of tumours from Snail1ME-KO mice favours an anti-tumourigenic phenotype." (PMID 37516803, 2023). "However, when CAFs were co-cultured with tumor cells, both cells have taken Dox, implying that the specific response of CAP NPs to FAP‐α could avoid off‐target effects and allow the released Dox to CAFs and the co‐existing tumor cells in TME." (PMID 36762192, 2023). "Furthermore, we also investigated the effect of FAP in fibroblast on tumor cells." (PMID 37325617, 2023). "Therefore, polyvalency may be an effective strategy for developing FAP-targeted radiopharmaceuticals with higher tumor uptake because of their increased FAP-recognition ability." (PMID 37321827, 2023). "Thus, we hypothesized that the focal increased levels of FGF20 in FAP(+) CAFs affect the neighbor tumor epithelial cells at the EOCC tumor invasive margin." (PMID 37964075, 2023). "Hence, we further analyzed the tumor stromal cells using the anti-FAP antibody." (PMID 36598731, 2023).
tumor (continued). "We rationalized that by removing unfavorable (4R)-fluoro substituent at the (2S)-4,4-difluoropyrrolidine-2-carbonitrile moiety, the resulting (4S)-mono-fluorinated version of FAPI-04 may have higher FAP-inhibitory potency and exhibit better FAP-mediated tumor uptake." (PMID 37110717, 2023). "Although a cautious dose escalation strategy will need to be taken, as there may be some patients who may be more likely to experience on-target, off-tumor toxicity (for example in the case of an unknown fibrotic process), our data to date suggest that FAP-CAR T cell therapy will be safe." (PMID 37607999, 2023). "However, the relatively short tumor retention time may hamper the use of FAP molecules for radioligand therapy applications." (PMID 37142301, 2023). "The higher hydrophilicity and smaller size of the pyridine-based pharmacophores compared to the quinoline-based pharmacophores could potentially lead to FAP-targeted tracers with faster pharmacokinetics, resulting in lower background uptake and higher tumor-to-background image contrast." (PMID 36986548, 2023). "However, it remained unclear whether the heterogeneous uptake pattern in individual tumors was a result of local differences in tumor perfusion or due to intratumoral inhomogeneity of FAP expression." (PMID 37370912, 2023). "Interestingly, we found that dual doses of FAP-CAR T cells not only slowed growth of the tumors but initially induced a degree of tumor regression compared to tumors in mice that received a first dose of FAP-CAR T cells with a subsequent dose of MigR control T cells." (PMID 37607999, 2023). "In addition, FAP has been reported to be overexpressed in a variety of cancers, such as lung, breast, and colorectal, making it an attractive antigen for the simultaneous targeting of tumor cells and respective CAFs present within the TME." (PMID 38102692, 2023). "However, due its high staining intensity from an autoradiography study on FAP-positive SK-Mel-187 human melanoma tumor xenografts, it might be a promising tool for oncology imaging." (PMID 36986548, 2023). "Results showed that the conditioned medium from FAP-over-expressed LX2 cells could significantly promote the cell invasion and migration rate of both MHCC97H and Sk-Hep1 cells as compared to NC group, suggesting that FAP in fibroblast is involved in tumor cell motility process in LIHC." (PMID 37325617, 2023). "However, recent studies revealed that in the disease state, FAP is localized to the surface of fibroblasts in the stroma, which accounts for more than 90% of tumor mass in various cancers, including malignant breast, colorectal cancer, skin cancer and bone sarcomas." (PMID 38313431, 2023). "In consequence, given the effective tumor half-life of 177Lu-FAP-2286 (mean, 44 h for bone and 32 h for single liver metastases), radionuclides such as 67Cu or 90Y (which has the additional advantage of a higher β-particle energy) may increase exposure as compared with 177Lu or 225Ac." (PMID 34168013, 2022). "Thus, the combination of FAP expression in tumor cells and CAFs should be assessed." (PMID 35818720, 2022). "Therefore, FAP is specifically expressed in the tumor microenvironment of more than 90% of epithelial tumors, especially in carcinomas characterized by a significant desmoplastic reaction (breast, colon, and pancreatic cancer), which contributes to cancer progression and poor disease prognosis." (PMID 35631416, 2022). "These FAP-expressing CAFs have been proposed to accelerate proliferation, invasion, and therapeutic resistance in ovarian cancer cells, and have also been suggested to reprogram tumor inflammatory environments in human intrahepatic cholangiocarcinoma via FAP-STAT3-CCL2 signaling." (PMID 36263225, 2022). "Interestingly not only the percentage of FAP-positive stromal cells was significantly higher in peritoneal metastases (39.2% vs 24.4%, P value = 1.64e-05) but also the percentage of FAP-positive tumour cells (1.5% vs 0.3%, P value = 1.73e-06)." (PMID 35296803, 2022).
tumor (continued). "It is hypothesized that FAPI-RGD would not only confer extra tumor specificity over other diseases, which is rationalized by the expression of both FAP and integrin αvβ3 in a variety of tumors; but also outperform its monomeric counterparts, with regard to tumor uptake and tumor retention." (PMID 36276644, 2022). "To further probe the function of FAP in tumor prognosis prediction, we conducted a series of pan-cancer studies including TCGA cohort patients and observed that high expression of FAP predicted adverse prognosis compared to low FAP expression at the pan-cancer level." (PMID 35359436, 2022). "Therefore, in TMA of GC, the tumor-promoting effect of FOXM1 and EZH2 in tumor cells may be correlated to the upregulation of FAP in CAFs." (PMID 36401232, 2022). "However, in cancer, they remain perpetually activated by a number of factors including the presence of cancer cells, as indicated by their expression of activation markers [e.g., α smooth muscle actin (αSMA), fibroblast activation protein (FAP)] and promote tumour progression via multiple pathways." (PMID 35479076, 2022). "Moreover, a similar result from a transplanted tumor model demonstrated that FAP + stromal cells could facilitate immunosuppression via ablation of T cell antitumor activity." (PMID 36092734, 2022). "Further strategies such as FAP-CAR-T cell therapy and FAP-targeted oncolytic adenovirus promote a specific immune attack against FAP + CAFs, upregulate pro-inflammatory cytokines, and increase antigen presentation, T cell function, as well as trafficking, leading to enhanced anti-tumor efficacy." (PMID 35488263, 2022). "In addition, our study also revealed the relationship between ICIs and different expressions of FAP in GC tumor tissues, which provides a new target for immunotherapy of GC, and provides new ideas and theoretical basis for basic research, clinical diagnosis, and individualized treatment of GC." (PMID 36010886, 2022). "Consequently, the radiotherapeutic approach using β-particles may be advantageous in terms of a broader destruction of the tumor mass over other FAP-targeting agents that only directly affect FAP-expressing CAFs." (PMID 35608703, 2022). "Since soluble factors released by tumor cells can induce CAF development in tumor tissue, we investigated whether the expression of FAP by primary fibroblasts can be affected by the soluble factors released by the murine NB cells NXS2-HGW used in our in vivo experiments." (PMID 36230765, 2022). "Interestingly, we and others have also identified FAP expression in a subset of tumour cells." (PMID 35296803, 2022). "In cancers of epithelial origin, FAP expression is mainly restricted to the CAFs in the tumor microenvironment, which possesses diverse functions, such as stromatogenesis, reciprocal signaling interactions with cancer cells, and crosstalk with tumor-infiltrating leucocytes." (PMID 35608703, 2022). "Furthermore, radiation selectively induced CXCL12, CXCR4 and FAPα expression in tumor tissues." (PMID 34976180, 2022). "Moreover, FAP+/F4/80+/HO-1+ stromal cells have been identified in a PAAD subcutaneous tumor model." (PMID 36263225, 2022). "In contrast to the results obtained after the depletion of FAP+ CAFs on a murine model of PCa, which presented delayed tumor growth and improved response to immunotherapy, the depletion the αSMAhi myCAF subset resulted in increased tumor progression and decreased survival." (PMID 36230505, 2022). "Inspired by this improved radiotherapeutic efficacy, this research focuses on investigating whether EB conjugation of FAPI-02 improves the efficacy of FAP-targeting radioligand therapy, especially in regards to tumor retention, tumor-to-normal tissue contrast as well as treatment response." (PMID 34987657, 2022).
tumor (continued). "It has been established that a DNA vaccine exclusively targeting FAP could suppress primary and metastatic tumor growth, promote the uptake of chemotherapeutic drugs and prolong the survival of tumor-bearing mice primarily by inducing CD8+ T cell-mediated killing of CAFs." (PMID 36324128, 2022). "Notably, we demonstrated that treatment of primary fibroblasts with FAPα/EBV-LMP1-containing exosomes derived from NPC cells activated fibroblasts by stimulating the functions of YAP1 and FAPα, thereby enhancing fibrotic responses and tumor growth in mouse xenografts." (PMID 35986369, 2022). "In addition, FAP-2286 maintained longer tumor retention and suppression in comparison to FAPI-46." (PMID 35608703, 2022). "Exposure to FAP and near-infrared laser radiation, with a mild elevation in localized temperature, induces the release of this agent at localized sites, thereby promoting the recovery of T lymphocyte activities within the immunosuppressive tumor microenvironment." (PMID 36263225, 2022). "The protumorigenic activity of FAP was accomplished through indirect enzymatic activity in the modulation of the extracellular matrix and a direct role in the transcriptional upregulation of related genes to promote tumor growth, tumoral vascularization and immune suppression." (PMID 34068501, 2021). "Interestingly, FAP expression in the cytoplasm and / or on the cell surface of the tumor cells could be observed in a subset of samples." (PMID 34050405, 2021). "Via enzymatic cleavage of its substrates, FAP plays an important role in extracellular matrix modulation, infiltrated macrophage education, metabolic regulation and tumor promotion; therefore, inhibiting the enzymatic activity of FAP may be a potential strategy of antitumor therapy." (PMID 34068501, 2021). "Thus, targeting FAP in this context might help regulate the tumor microenvironment and permit a more effective anti-tumor immune response." (PMID 34490078, 2021). "This, together with the immunofluorescence studies proving HFn-FAP targeting of CAFs in vivo, suggest that the functionalization with FAP is able to trigger a specific CAF recognition in the tumor that, at the same time, might also enhance intratumoral retention of the particles." (PMID 33562504, 2021). "Interestingly, FAP+ PSCs may play a role in suppressing T-cell activity, hence making them an ideal target to increase the anti-tumor immune response." (PMID 33499238, 2021). "We used aCGH/SNP to evaluate whether genetic alterations characteristic of GBMs are present in the isolated FAP-expressing cell cultures, i.e., whether these cells represent normal stromal cells recruited into the tumours or arise instead by transdifferentiation of transformed cells." (PMID 34282761, 2021). "Findings, mainly derived from preclinical studies, suggest that the inhibition of FAP-enzymatic activity induced by low molecular weight inhibitors has the potential to decrease the invasiveness of malignant cells and further lead to a considerable reduction of the tumor growth." (PMID 34681246, 2021). "Moreover, the abundance of Treg cells within the tumor region was observed, as well as the depletion of helper T (Th1) cells and NK cells, indicating an immunosuppressive environment induced by secreted components from FAP positive cells." (PMID 34681246, 2021). "It is also worth noting that fibroblast activation protein-a (FAP) is highly overexpressed on cancer-associated fibroblasts, and it has been shown that targeting cancer-associated fibroblasts by anti-FAP CAR T cells inhibits tumor growth and augments host immunity against tumor." (PMID 34177890, 2021). "Nevertheless, the direct role of FAP expression on tumor cells in the regulation of cell proliferation through intracellular signaling pathways remains to be investigated, and studies on the enzymatic role of FAP on cells other than tumor cells within the GBM microenvironment remain to be addressed." (PMID 34068501, 2021).
tumor (continued). "In this work we demonstrated a strong association between the tumor loss of HLA-I and the formation of a “non-permissive” tumor microenvironment characterized by reduced immune infiltration and strong stromal reaction with increased presence of FAP+ stroma cells." (PMID 34298868, 2021). "Hence, targeting this protein with several probes, including antibodies, immunoconjugates, and small molecular FAP inhibitors, may be an interesting approach for tumor detection and suppression." (PMID 34959613, 2021). "Besides, it is hypothesized that with the insertion of anti-FAP BiTE gene downstream of STAT4 responsive promoter, FAP antigen could be locally targeted on CAFs surface in the tumor microenvironment." (PMID 34177890, 2021). "Although imaging of FAP showed great promise in both preclinical studies and clinical trials, the therapeutic efficacy of the fibroblast activation protein inhibitor alone is still limited due to a relatively short retention time of the corresponding radiopharmaceuticals in the tumor area." (PMID 34681246, 2021). "FAP is a transmembrane glycoprotein enzyme, which is overexpressed on the cell surface of activated CAFs of multiple tumor types and, in particular, in many epithelial carcinomas (especially in those characterized by a strong desmoplastic reaction, as they can comprise up to 90% of the tumor mass)." (PMID 34681850, 2021). "Systemic biodistribution of HFn-FAP demonstrated that nanoparticles were also captured by the liver during the first hours post-injection, as shown by intense fluorescence signal in this organ that almost covered the fluorescence of the tumor when imaging the mice in vivo." (PMID 33562504, 2021). "Therefore, FAP is a broad-spectrum tumor target with strong specificity and good stability." (PMID 33816303, 2021). "As stroma occupies a major part in the tumor volume, FAP-targeted radiotracers may increase the target sensitivity and image contrast of the disease area compared to the targeting of glucose metabolic pathway in cancer cells solely due to their lack of brain uptake in contrast to [18F]FDG." (PMID 34681246, 2021). "In this regard, the Bis-FAP/End-IL should accumulate in both tumor models based on binding to murine FAP expressing stromal cells such as myofibroblasts and pericytes and also to the murine endoglin expressing endothelial cells that make up the tumor vasculature." (PMID 32316521, 2020). "FAP-driven binding enables docking of RO6874813 on cancer-associated fibroblasts increasing the local concentration of DR5 binding hyperclustering to potently induce apoptosis in tumor cells but not in normal cells." (PMID 32989604, 2020). "Hence, while FAP targeting CAR-T cells therapy resulted in tumor regression due to enhanced anti-tumor immunity, it also may cause failure of immunosurveillance and alterations in normal tissues, resulting in lethal toxicity anemia and cachexia." (PMID 32151052, 2020). "Therefore, radiolabeled, FAP-specific inhibitors might be promising tumor-targeting radiopharmaceuticals in NETs." (PMID 33207788, 2020). "Although two FAP-targeted fluorescent imaging agents have already been reported in the literature 53, 25, both agents rely on the catalytic activity of FAP (a serine proteinase) to release the fluorescent dye from a quencher without providing any mechanism to retain the released dye in the tumor." (PMID 32483418, 2020). "Expression of FAP was most striking in regions annotated as ‘hyperplastic blood vessels’ or ‘microvascular proliferation’, although expression in the main tumor parenchyma (‘cellular tumor’) and at the interface between tumor and normal tissue (‘infiltrating tumor’) was also notable." (PMID 33082953, 2020). "Finally, since FAP expression is likely limited to CAFs within the tumor micro-environment, the ability of the FL-L1-TubBH conjugate to completely eradicate the tumor emphasizes on the vital role CAFs play in tumor survival." (PMID 32483418, 2020).